MIR92A1 (microRNA 92a-1)
Synonyms: hsa-mir-92-1; hsa-mir-92a-1; C13orf25; MIR92-1; MIRH1; MIRHG1; MIRN92-1; MIRN92A-1; MIRN92A1; miRNA92-1; mir-92a-1
Gene: MicroRNA gene on chromosome 13 (91,351,314 to 91,351,391, forward strand). Ensembl gene ENSG00000283705.
Gene Ontology:
Biological process: miRNA-mediated post-transcriptional gene silencing
Cellular component: RISC complex
Homologues: Orthologues: chimpanzee ptr-mir-92-1 (100% identical), guinea pig MIR92A1 (100% identical), macaque mml-mir-92a-1 (100% identical), rabbit MIR92A1 (99% identical), rat Mir92a1 (95% identical), tropical clawed frog xtr-mir-92a-1 (82% identical), zebrafish mir92a-1 (82% identical), zebrafish mir92a-2 (72% identical). Paralogues in human: MIR92A2 (46% identical), MIR25 (40% identical).